GSC2 (goosecoid homeobox 2)
Description:
May have a role in development. May regulate its own transcription. May bind the bicoid consensus sequence TAATCC.
Synonyms: GSCL
Tractability: No criterion of Open Targets' tractability assessment is met for any kind of drug.
Gene: Protein-coding gene on chromosome 22 (19,146,993 to 19,150,292, reverse strand). Ensembl gene ENSG00000063515.
Subcellular location: Nucleus
Gene Ontology:
Molecular function: DNA-binding transcription factor activity; protein binding; sequence-specific DNA binding; sequence-specific double-stranded DNA binding; DNA binding; DNA-binding transcription factor activity, RNA polymerase II-specific; RNA polymerase II cis-regulatory region sequence-specific DNA binding
Biological process: regulation of transcription by RNA polymerase II; anatomical structure morphogenesis; regulation of DNA-templated transcription
Cellular component: chromatin; nucleus
Genetic constraint (gnomAD): Loss-of-function variants: 10 observed, 7.39 expected, observed/expected ratio (o/e) 1.35, 90% interval 0.81 to 1.9. That is too few expected variants to judge how well the gene tolerates losing a copy. Missense variants: 204 observed, 133.6 expected, observed/expected ratio (o/e) 1.53, 90% interval 1.36 to 1.72. Synonymous variants: 98 observed, 61.35 expected, observed/expected ratio (o/e) 1.6, 90% interval 1.36 to 1.87.
Homologues: Orthologues: chimpanzee GSC2 (99% identical), macaque GSC2 (91% identical), dog GSC2 (83% identical), pig GSC2 (81% identical), mouse Gsc2 (75% identical), rat Gsc2 (66% identical), guinea pig GSC2 (64% identical), tropical clawed frog GSC2 (41% identical). Paralogues in human: GSC (40% identical), ARX (31% identical), VSX2 (30% identical), ISX (27% identical), RAX (26% identical), ALX4 (26% identical), PAX7 (25% identical), PITX1 (25% identical), PITX2 (25% identical), PITX3 (25% identical), UNCX (25% identical), DMBX1 (24% identical), and 38 more.
Diseases named in the same sentence as GSC2 in open-access papers:
GSC2 is named in the same sentence as 2 diseases in open-access papers, as found by Europe PMC text mining. Sharing a sentence is not in itself a finding about the gene and the disease.
GSC2 shares sentences with these, for which no sentence is quoted: tumor (2 papers); cancer (1).